MMP2 (matrix metallopeptidase 2)
Diseases named in the same sentence as MMP2 in open-access papers (continued):
Sharing a sentence is not in itself a finding about the gene and the disease.
ovarian carcinoma (continued). "Here, we observed that minocycline suppressed multistep of ovarian cancer cell metastasis processes including migration, invasion and adhesion ability in a concentration-dependent manner which was coupled with down-regulation of MMP-2 and MMP-9 proteins." (PMID 23593315, 2013). "Previous studies indicated that miR-138 may have an effect on tumor metastasis by targeting SOX4 and Hif1a in ovarian cancer, MMP2/MMP9 in cholangiocarcinoma cells and FAK in hela cells." (PMID 24171926, 2013). "The experimental results show that the expression of MMP-2 was up-regulated in ovarian cancer." (PMID 24245968, 2013). "Similarly, studies concerning the correlation of claudin-6, occludin and MMP-2 with ovarian cancer have rarely been reported." (PMID 24245968, 2013). "In the pathogenesis of ovarian cancer, MMP-2 and MMP-9 are consistently upregulated." (PMID 22022379, 2011). "Our results indicate that gelatinolytic activities of MMP-2 or MMP-9 are not required for collagen I invasion by ovarian cancer cells as treatment with the MMP-2/MMP-9 inhibitor SB-3CT caused only a small reduction in invasion." (PMID 17609667, 2007). "We report that ovarian cancer spheroids secrete much greater amounts of both pro-MMP2 and MMP9 compared to cells grown as a monolayer, and in the case of spheroids, both MMP2 and MMP9 were present in the active form, while monolayer cells only secreted the inactive precursors." (PMID 17567918, 2007). "MMP2 and 9 are expressed in the ascites and plasma of ovarian cancer patients." (PMID 17567918, 2007). "Inhibition of PCDGF by antisense PCDGF transfection could downregulate the expression of cyclin D1, CDK4 and MMP-2, and markedly reverses malignant phenotype of ovarian cancer." (PMID 17261172, 2007). "In a human ovarian cancer cell line A2780, fruit juice as well as the polyphenols of pomegranate such as ellagic acid and luteolin suppressed cell proliferation and migration via downregulation of matrix metalloproteinases (MMP-2 and 9) albeit in a concentration-dependent way." (PMID 38027211, 2023). "Notably, cisplatin and baicalein may suppress MMP2 protein expression and cell metastasis of resistant ovarian cancer through regulating the CirSLC7A6/miR-2682-5p/SLC7A6 axis." (PMID 37940982, 2023). "Moreover, IHC staining showed the invasion marker MMP-2, MMP-9, Ki67 and PCNA were down-regulated by the loss of LINC00852, suggesting LINC00852 could promote the invasion of ovarian cancer in vivo." (PMID 34496800, 2021). "In ovarian cancer, high mRNA expression of MMP-2, -9, -14 and TIMP-2 was reported in ovarian tumors, and correlated with low survival in patients, indicating that the expression of these genes may act as suitable nominators of survival in advanced-stage patients." (PMID 35047406, 2021). "Moreover, AR expression reduces patient survival whenever the protective effect of MMP-2 in the tumor stroma was absent; therefore, a deleterious effect mediated by AR associated to MMPs should be considered in ovarian cancer studies." (PMID 32718331, 2020). "Previous studies indicate that DHA inhibits the growth and progression of ovarian cancer by down‐regulating pFAK and MMP‐2;11 however, the underlying mechanisms through which DHA down‐regulates pFAK and MMP‐2 to inhibit epithelial ovarian cancer remain unclear." (PMID 30338663, 2018). "MMP-2 is also found to be abundantly expressed by the multicellular aggregates derived from ascites and is thought to play a major role in early metastasis by facilitating the rapid disaggregation of the ovarian cancer cells for adhesion to the mesothelial surface." (PMID 29393911, 2018). "The systematic review on 12 polymorphisms suggested that MMP2 C-735T, MMP7 A-181G, MMP8 rs11225395, MMP9 rs6094237, MMP12 rs2276109, MMP20 rs2292730, MMP20 rs12278250, MMP20 rs9787933 might have a potential effect on ovarian cancer risk." (PMID 28957437, 2017).
ovarian carcinoma (continued). "MMP-2 is believed to be involved in two aspects of the ovarian cancer spread process: It helps tumor cells penetrate the basement membrane of the ovary to invade the stroma, and may enable the tumor cells to detach from the epithelial surface and migrate into the peritoneal cavity." (PMID 23384043, 2013). "Claudin-6 and MMP-2 may play a positive role in the invasion and metastasis of ovarian cancer." (PMID 24245968, 2013). "Our present study shows that claudin-6 and MMP-2 were both up-regulated in ovarian cancer, MMP-2 expression was enhanced with increased clinical stage and metastasis indicates that claudin-6 and MMP-2 may play an important role in the progression of ovarian cancer." (PMID 24245968, 2013). "As our previous study, our results revealed reduced expression of MMP2 in OVCAR3 and SKOV3 ovarian cancer cell lines treated with DNC (P < 0.01), OXA (P < 0.001) and combination of them (P < 0.01)." (PMID 41480643, 2026). "Several studies have shown the upregulation of MMPs, such as MMP2 and MMP9, in ovarian cancer tissues compared to normal or benign ovarian tissues, and their expression levels correlate with clinical stage, tumor invasiveness, and metastatic potential." (PMID 40558552, 2025). "In ovarian cancer, RBP4 overexpression stimulates the expression of MMP-2 and MMP-9, which increases the migration of tumor cells and affects the unfavorable prognosis." (PMID 41007818, 2025). "The compound formulation inhibits ovarian cancer cell invasion and metastasis by down-regulating the protein expression of HIF-α, MMP-2, MMP-9, and E-cadherin, demonstrating significantly in vivo pharmacodynamic effects." (PMID 40490812, 2025). "Previous work suggested SOX2 regulates tumorigenic features and EMT processes by modulation of MMP2 and MMP9 activity in human CRC and ovarian cancer cells." (PMID 40179020, 2025). "In a similar study, auraptene, a natural coumarin mainly obtained from Citrus spp., was shown by gel zymography to dose-dependently inhibit the activities of both MMP-2 and MMP-9 in both human ovarian cancer (A2780) and cervical cancer (HeLa) cell lines." (PMID 39364049, 2024). "Functionally, TGFBI affected the migration and invasion of ovarian cancer cells by regulation of epithelial mesenchymal transition (EMT) markers (CDH1 and CDH2) and extracellular matrix (ECM) degradation proteins (MMP-2)." (PMID 38395907, 2024). "Among gelatinases, MMP2 expression was downregulated, while the MMP9 level was significantly higher in ovarian cancer." (PMID 38397798, 2024). "In conclusion, we are the first team to study the significance of MMP-2, MMP-3, MMP-11 and MMP-26 as new markers of ovarian cancer in comparison not only to HE4 and CA125, but also to the ROMA algorithm." (PMID 38892452, 2024). "In previous studies, we also found that TMEFF1 promotes the expression of N-cadherin, Vimentin, MMP2, and MMP9 in ovarian cancer cells, inhibits the expression of E-cadherin, and participates in the EMT process." (PMID 38468232, 2024). "Conversely, down-regulating MMP2 and MMP9 has been shown to reduce metastasis and migration in retinoblastoma, bladder, oral, and ovarian cancer cells." (PMID 40066127, 2024). "Accordingly, we also found that TGFBI KO in SKOV3 and Caov-3 cells led to decreased expression of MMP-2, which inferred that TGFBI had the potential of remodeling ECM in ovarian cancer microenvironment." (PMID 38395907, 2024). "Most of the tested metalloproteinases upregulated mRNA expression in both FIGO I/II and FIGO III/IV stages of ovarian cancer (MMP1, MMP13, MMP2, MMP9, MMP10, MMP7, MMP12 and MMP14) indicating profound modifications of the extracellular matrix." (PMID 38397798, 2024). "The present study investigated the effect of DNC, Oxa, and combination treatments of these two agents on the mRNA and protein expression levels of MMP-2 and MMP-9, as two documented MMPs correlated with ovarian cancer progression." (PMID 36658640, 2023).
ovarian carcinoma (continued). "CircATRNL1 absorbs miR-378, activates Smad4, and further decreases the activities of Akt, Cyclin D1, MMP2 and MMP9, thereby inhibiting proliferation, angiogenesis and metastasis of ovarian cancer cells." (PMID 37940982, 2023). "According to Zhu, harmine was able to inhibit cell migration by reducing MMP-2 and MMP-9 expression levels in glioblastoma, and Gao reported that harmine inhibited MMP-9 expression in ovarian cancer cells." (PMID 37175359, 2023). "DAB2 expression had significant positive correlations with mesenchymal markers (ZEB2, TGFβ1, SNAI2, ZEB1, FN1, MMP2, TWIST1 and MMP3) and CSC markers (CD44 and MYD88) in ovarian cancer cell lines (CCLE) and tissues (TCGA: RNA sequencing and microarray)." (PMID 37815603, 2023). "Matrix metalloproteinase (MMP)-2 and MMP-9 play important roles in various steps of metastasis in human ovarian cancer cells." (PMID 37507925, 2023). "Treating SKOV-3 cells with either GnRH1 or GnRH2 led to reduced MMP-2 expression and increased secretion of tissue inhibitor of MMP-2 (TIMP2), both important mediators of ovarian carcinoma metastasis." (PMID 38260130, 2023). "In ovarian cancer, TP73‐AS1 was showed to promote cell survival and metastasis via increasing MMP2 and MMP9 expressions." (PMID 35871358, 2023). "In accordance with the previous reports of MMP expression for the progression of the ovarian cancer, we have tested the effect of DNC, Oxa, and its combination on the differential expression of MMP-2 and MMP-9." (PMID 36658640, 2023). "In particular, MMP2 and MMP9 can degrade collagen IV, the major ECM component, and play important roles in ovarian cancer." (PMID 35621926, 2022). "In that context, we have shown enhanced secretion of MMP-2 and MMP-9 in ovarian cancer cells cultured as spheroids compared to monolayer cultures." (PMID 36585738, 2022). "VEGFA, PLAU, MMP2, MMP9, and MMP14 expression levels were reduced by stigmasterol treatment, which exerted a complex anticancer effect in the context of ovarian cancer." (PMID 35379271, 2022). "In our research, we noted an increase in MMP2 and MMP10 expression under the influence of exosomes derived from ovarian cancer cells." (PMID 36012171, 2022). "Several genes have been confirmed to be closely related to the occurrence and progression of ovarian cancer, including SNAI2, VCAM1, BRCA1, MMP2, MECOM, MXS1, PARP1 and so on." (PMID 35090503, 2022). "Recent studies have demonstrated certain anticancer strategies to inhibit the expression of pro-invasive factors, MMP2 and MMP9, in ovarian cancer using natural compounds." (PMID 35621926, 2022). "An intensification in p38 mitogen-activated protein kinase (MAPK) activity and a dose-dependent decrease in the matrix metalloproteinase-2 (MMP2) protein level were shown to limit cell the proliferation of OVCAR-3 and migration in human ovarian cancer cells." (PMID 36386196, 2022). "The expression of N-cadherin, vimentin, MMP2 and MMP9 was significantly reduced when ZNF252P-AS1 was inhibited in ovarian cancer cells, whereas E-cadherin was dramatically up-regulated." (PMID 34980214, 2022). "Our results suggest that the inhibition of TIMP-2 by siRNA and CRISPR/Cas-9 modulate the expression of MMP-2 and MMP-14 and reprogram ovarian cancer cells to facilitate proliferation and invasion." (PMID 36585738, 2022). "MMP2 and MMP9 are the members of matrix metalloproteinases family, which is closely related to poor prognosis in ovarian cancer patients." (PMID 34980214, 2022). "Our findings suggest that citromycin inhibits the migration and invasion of human ovarian cancer cells by downregulating the expression levels of EMT markers and MMP-2/9 via inhibition of the ERK1/2 pathway." (PMID 35621926, 2022). "In the present work, the elimination of ZNF252P-AS1 exhibited decreased expression of MMP2 and MMP9 in ovarian cancer." (PMID 34980214, 2022).
ovarian carcinoma (continued). "After treatment, the peritoneal spread of the ovarian cancer mouse model was significantly inhibited, and extracellular regulated protein kinases (ERK) phosphorylation and matrix metallopeptidase 2 (MMP2) expression in tumors were reduced." (PMID 36297672, 2022). "Here, the authors found that TRIM47 knockdown reduced STAT3 phosphorylation at Tyr705 in both cultured and xenografted ovarian cancer cells, followed by reduced expression of the STAT3 target genes MCL-1, MMP2, and c-MYC." (PMID 36288633, 2022). "Other investigations have revealed that resistin stimulates the growth of ovarian cancer cells, increases their invasive potential, and enhances the secretion of the angiogenesis markers VEGF and MMP-2 by tumor cells." (PMID 35453670, 2022). "Co-culture of human omental ADSCs and SKOV3 ovarian cancer cells increased cancer cell proliferation and migration via an increased ADSC secretion of MMP-9 and MMP-2." (PMID 34440886, 2021). "For instance, it is stated that suppression of the ERK and CREB pathway down-regulates transcriptional expressions of gelatinases (MMP-2 and MMP-9) in ovarian cancer cells." (PMID 33671187, 2021). "Through down-regulation of MMP2 and 9 paralleled by up-regulation of their inhibitors (TIMP2 and 3), Pug attenuated the migratory potential of human cervical and ovarian cancers." (PMID 34444893, 2021). "We have also reported previously an enhanced secretion of MMP-2 and MMP-9 by floating ovarian cancer spheroids, with diminished expression of several integrins." (PMID 35047406, 2021). "Akt activation is also needed for migration and invasion of SKOV-3 ovarian cancer cells, as the selective inhibition of the PI3K/Akt by LY294002 significantly suppressed expression of MMP-2." (PMID 33671187, 2021). "The MMP-2 inhibition by presence of TCF21 in ACC cells was also reported in colon rectal and ovarian cancer cells, showing the TCF21 properties in decrease cell invasion of different types of tumors through inhibition of MMP-9 and MMP-2." (PMID 35201460, 2021). "Studies have pointed out that PAK4 modulates ovarian cancer tumor progression via c-Src/ERK1/2 and EGFR/MMP2 signal pathway." (PMID 32549768, 2020). "For example, MMP2 and MMP14 production is stimulated by the ovarian cancer cells while that of MMP1 is enhanced by the gastric cancer cells." (PMID 32780245, 2020). "Our immunoblot analysis revealed decreased expression levels of MMP‐2 and MMP‐9 in UGDH‐silenced ovarian cancer cells, which is consistent with previous reports." (PMID 32893977, 2020). "In our study, we found that HE4 knockdown inhibited the expression of MMP-2 and MMP-9 in ovarian cancer cells." (PMID 31477564, 2019). "Western blot analyses showed that knockdown of HE4 reduced the levels of matrix metalloproteinases (MMP-2 and MMP-9) and inhibited epithelial to mesenchymal transition (EMT) in ovarian cancer cells." (PMID 31477564, 2019). "In contrast, the inhibition of SERPIND1 expression in ovarian cancer cells reduced the phosphorylation of PI3K/AKT, increased E-cadherin expression, and reduced the expressions of N-cadherin, Vimentin, MMP2, and MMP9." (PMID 31637210, 2019). "Several studies reported that LPA increases the expression of MMP-2 or MMP-9 in leukemic monocytes 32, neuroblastoma 33, hepatocellular carcinoma cells 34, and ovarian cancer cells." (PMID 31534541, 2019). "To further analyze the role of SERPIND1 in ovarian cancer cells, we examined the major proteins of epithelial–mesenchymal transition (EMT), including MMP2, MMP9, Vimentin, N-cadherin, and E-cadherin." (PMID 31637210, 2019). "In 2003, a study reported that pFAK and MMP‐2 were downstream targeting genes of the hedgehog signaling pathway that induces cell migration and invasion through activation of FAK in ovarian cancer." (PMID 30338663, 2018). "MMP2 and MMP9 have also been reported to be correlated with poor survival in ovarian cancer patients and promoted ovarian cancer cell invasion." (PMID 30453504, 2018).
ovarian carcinoma (continued). "They observed with in vitro studies that this conjugate exerts a high cytolytic effect on ovarian cancer cells (SKOV-3), cells that possess a strong MMP2 activity, and decreased activity on normal L-cells that possess low MMP2 activity." (PMID 29562696, 2018). "The MMP-2, MMP-3, and MMP-9 expression levels were next examined in the cocultivation of SKOV3 and WS1 to mimic the interaction of ovarian cancer cell with stromal cells." (PMID 29390034, 2018). "Both MMP-2 and MMP-9 were enhanced in one of the ovarian cancer cell lines (SKOV3) in response to gonadotropins, while TIMP-1 and TIMP-2 were down regulated, suggesting an inverse relationship between MMPs and their endogenous inhibitors." (PMID 29393911, 2018). "According to previous studies on ovarian cancer biomarkers, FBN1 and MMP2 were found to be metastasis-promoting markers that were stimulated or suppressed by Aurora-A or BRCA2." (PMID 28562334, 2017). "NEAT1 knockdown in ovarian cancer cells resulted in a decrease in Snail1, TGF-β1, MMP-2 and MMP-9 and so presumably promotes EMT in ovarian cancer." (PMID 28430163, 2017). "Co-transfection of TCF21 expression plasmid with miR-205 mimic diminished the inhibitory effect of TCF21 on MMP-2 and MMP-10 in ovarian cancer cells." (PMID 28476165, 2017). "In conclusion, EZH2 promotes ovarian cancer migration and invasion via the epigenetic silencing of TIMP2 by H3K27me3 and DNA hypermethylation, which leads to the activation of MMP2 and MMP9." (PMID 28620234, 2017). "VEGF regulates ovarian cancer invasion and migration in vitro through VEGFR-mediated secretion and activation of MMP-2, MMP-7, and MMP-9." (PMID 28476025, 2017). "Our results showed that MMP-2, MMP-7, MMP-9 and MMP-10 expression were significantly up-regulated in ovarian cancer tissue compared with normal ovarian tissues." (PMID 28476165, 2017). "We found that miR-519d transfection decreased MMP2, MMP9, STAT3, and HuR expression in ovarian carcinoma cells; at the same time, E2F1 increased the expression of these genes." (PMID 28146423, 2017). "As a previous study reported, MMP2 and MMP9 participate in the initiation of omentum metastasis in ovarian cancer." (PMID 29221185, 2017). "Consistently, Huang and Sui showed that the positive rate of MMP-2, vascular endothelial growth factor C (VEGF-C) and E-cadherin in ovarian cancer is higher than that in benign and borderline ovarian tumors." (PMID 28538838, 2017). "As the member of MMPs family, the role of MMP-2 and MMP-9 in prostate cancer has been extensively studied, there are still multiple evidence that shed light on the MMPs and their impact on ovarian cancers." (PMID 28476025, 2017). "In conclusion, our study identifies a novel molecular mechanism for E2F1, whereby it targets miR-519d to upregulate RhoC, Bcl-2, cyclin D1, survivin, MMP2, MMP9, STAT3 and HuR expression, promoting tumorigenesis and progression in ovarian carcinoma." (PMID 28146423, 2017). "In this study with long-term follow-up, the independent prognostic value of MMP-14 and MMP-2 expression in ovarian cancer is limited to a role in PFS for stromal MMP-14 expression and epithelial MMP-2 expression." (PMID 27038607, 2016). "Some studies have been published on the prognostic value of MMP2, MMP7 and TIMP2 in ovarian cancers, but it is still controversial." (PMID 27835587, 2016). "Having investigated a regional cohort of 94 ovarian cancer patients by means of semiquantitative immunohistochemistry for MMP-14 and MMP-2, we found that epithelial MMP-14 and epithelial MMP-2 expression correlate." (PMID 27038607, 2016). "We have previously shown that enhanced expression of α2β1 integrin in ovarian cancer spheres facilitates sphere disaggregation, pro-MMP-2/9 expression and MMP-2/9 activation." (PMID 27390927, 2016). "In this module, 5 genes (FN1, MMP2, MMP1, PLAU, and SPARC), colored in green, were identified as ovarian cancer-related genes in the DDOC database." (PMID 25611546, 2015).